RBP4 (retinol binding protein 4)
Diseases named in the same sentence as RBP4 in open-access papers (continued):
Sharing a sentence is not in itself a finding about the gene and the disease.
atherosclerosis (continued). "RBP4 concentrations were related to enhanced atherosclerosis in patients with generalized or/and abdominal obesity." (PMID 24651174, 2014). "Independent relationships of retinol binding protein 4 concentrations with endothelial activation and atherosclerosis." (PMID 24651174, 2014). "Although, the involvement of RBP4 in the development of subclinical atherosclerosis has been proven, its prognostic value in carotid or coronary atherosclerosis progression is still obscure." (PMID 25142320, 2014). "RBP4 levels independently predicted early endothelial dysfunction, linking adipose tissue inflammation and subclinical atherosclerosis." (PMID 25479076, 2014). "Independent relationships of retinol binding protein 4 concentrations with those of E-selectin and atherosclerosis amongst subgroups." (PMID 24651174, 2014). "In this study, we evaluated the association of serum lipocalin-2 and RBP4 with intima-media thickness (IMT) and subclinical atherosclerosis in type 2 diabetic patients." (PMID 23799122, 2013). "The published literature regarding the relationships between retinol-binding protein 4 (RBP4) and cardiometabolic risk factors and subclinical atherosclerosis is conflicting, likely due, in part, to limitations of frequently used RBP4 assays." (PMID 22587616, 2012). "Early research concentrated on topics such as cardiovascular risk (cluster 3), theca-interstitial cells (cluster 7), children (cluster 8), retinol-binding protein 4 (cluster 9), atherogenesis (cluster 10), adipocytokines (cluster 11), atherosclerosis (cluster 13), and IR (cluster 14)." (PMID 41209444, 2025). "We have identified seven genes (CHI3L1, CD36, LEPR, RETN, IL-18, RBP-4, and RARRES2) that may be associated with IR and atherosclerosis as having possible evidence based on the disease pathogenesis of ED and inflammation." (PMID 36984867, 2023). "Since high molecular weight adiponectin, leptin and RBP-4 did not have statistically significant associations with subclinical atherosclerosis, they were not included in the further analysis." (PMID 37512134, 2023). "The results suggested that RBP4 was involved in the progression of atherosclerosis." (PMID 35309061, 2022). "It has been suggested that RBP4 plays a role in the development of atherosclerosis." (PMID 36304097, 2022). "In our study, atherosclerosis of the aorta was observed in HE staining after injection of recombinant RBP4 in diabetic rats, which suggests that RBP4 may be involved in the occurrence of diabetic macroangiopathy." (PMID 35082965, 2022). "All these results suggest that RBP4 may be involved in the pathophysiological process of atherosclerosis by altering the distribution of proatherosclerotic plasma lipoproteins." (PMID 35309061, 2022). "Epidemiological studies suggested that RBP4 might be involved in the pathogenesis of atherosclerosis." (PMID 35369314, 2022). "In an atherosclerosis study, RBP4 is positively correlated with NF-κB, and RBP4 may participate in the inflammatory pathway by regulating NF-κB signaling." (PMID 36267567, 2022). "Therefore, the exact actions of RBP4 in atherosclerosis progression and vascular homeostasis are still warranted." (PMID 34758835, 2021). "Retinol-binding protein-4 (RBP-4) is a proinflammatory cytokine that may involve in the progression of IR, T2D, atherosclerosis and CAD." (PMID 34571734, 2021). "Results of the multivariate logistic regression analysis revealed that RBP4 and SBP were risk factors for atherosclerosis and HDL-c might represent as a protective factor." (PMID 30186876, 2018). "Retinol binding protein 4 (RBP4) promotes the pathogenesis of atherosclerosis." (PMID 29269856, 2017). "However, there are studies that showed that RBP4 positively and significantly correlates to carotid intima-media thickness, which is an atherosclerosis indicator, and negatively correlates to flow-mediated dilatation." (PMID 24604418, 2014).
atherosclerosis (continued). "Further recent studies in experimental models of high cardiovascular risk in humans have actually exhibited a protective role of RBP4 in vasculature, or even reduced levels in men with AMI, which add to the controversy concerning the actual role of RBP4 in atherosclerosis." (PMID 25142320, 2014). "Further, although RBP4 concentrations were lower in black compared to white patients, they were associated with atherosclerosis in the former but not the latter." (PMID 24651174, 2014). "The results from the present and previous studies indicate that RBP4 has a prominent role as a modulator of atherosclerosis in hyperinsulinemia, and may contribute to a better understanding of the numerous unexpected aspects of CVDs." (PMID 24604418, 2014). "Our study revealed an independent correlation between subclinical atherosclerosis and serum lipocalin-2 and RBP4 levels in type 2 diabetic patients, suggesting that these lipocalins might be involved in the early stage of diabetic vascular complications." (PMID 23799122, 2013). "Third, elevated RBP4 in aortic atherosclerotic lesions from both human and mice could facilitate the formation of macrophage-derived foam cell in way of activating cholesterol uptake, thus accelerating the progression of atherosclerosis." (PMID 35369314, 2022). "However, retinol-binding protein 4 contributes to IR and atherosclerosis in T2DM and could be used as an early predictor of CVD." (PMID 34836405, 2021). "Likewise, RBP4 was reported as the predictor of atherosclerosis in patients with RA." (PMID 33461622, 2021). "However, whether RBP4 is involved in insulin-induced proliferation of VSMCs leading to atherosclerosis remains unclear." (PMID 24604418, 2014). "This review focuses on the link between IR, T2DM, atherosclerosis, CAD, and the potential genetic markers CHI3L1, CD36, LEPR, RETN, IL-18, RBP-4, and RARRES2 genes." (PMID 36984867, 2023). "This review identified CHI3L1, CD36, LEPR, RETN, IL-18, RBP-4, and RARRES2 genes as the potential genetic markers of IR and atherosclerosis in T2DM patients with CAD." (PMID 36984867, 2023). "Adipose tissue-derived factors, known as adipokines (such as adiponectin, leptin, resistin, retinol-binding protein 4 (RBP-4) and visfatin), influence atherosclerosis development and can have either protective or aggravating effects." (PMID 37512134, 2023). "Thus, it suggests that retinol-free RBP4 may be involved in the atherosclerosis process." (PMID 32718041, 2020). "By measuring the circulating retinol-binding protein 4 (RBP4), transthyretin (TTR) and the cIMT, a link between vitamin A and subclinical atherosclerosis was shown." (PMID 32283588, 2020). "Results of our study suggested that RBP4 was associated with risk factors of cardiovascular disorders such as HOMA-IR, TG, SBP, CRP, AI1, and AI2 and was a predictor for diabetic atherosclerosis, which implied that RBP4 could involve in many pathways on the formation of atherosclerosis." (PMID 30186876, 2018). "Further, the relationship between serum levels of RBP4 and oxidative stress injury and the degree of atherosclerosis in elderly patients with cerebral infarction has not been reported in the literature." (PMID 36304097, 2022). "Growing evidence about the role of RBP4 in lipid metabolism and atherosclerosis is well known, but the data are not clearly defined; also, both atherogenic and cardioprotective effects of RBP4 have been described." (PMID 34575030, 2021). "Third, RBP4 levels independently predicted early endothelial dysfunction, linking adipose tissue inflammation and subclinical atherosclerosis in non-diabetic individuals." (PMID 30038059, 2018). "Overall, a potential correlation between RBP4 and atherosclerosis and CHD can not be unequivocally claimed." (PMID 24604418, 2014). "More recently, RBP4 levels independently predicted early endothelial dysfunction, linking adipose tissue inflammation and subclinical atherosclerosis in non-diabetic individuals." (PMID 25142320, 2014).
atherosclerosis (continued). "However, the regulatory roles of circulating lipocalin-2 and RBP4 in type 2 diabetic patients with or without subclinical atherosclerosis have not been reported yet." (PMID 23799122, 2013). "Thus, on day 21 of HDBR, the levels of RBP4, APOB and C3 proteins increased, each of which plays an important role in one way or another in modulating the properties of the endothelium and contributing to the development of atherosclerosis, which is a precursor of many cardiovascular diseases." (PMID 38966226, 2024).
Hypertension (49 papers, 2012 to 2025). The presence of chronic increased pressure in the systemic arterial system. "Several clinical investigations showed that higher RBP4 levels in subjects are related to hypertension and associated with endothelial dysfunction." (PMID 37512089, 2023). "Our findings suggest a hypertension-dependent relationship between plasma retinol and cardiometabolic risk and complex interactions of RBP4 with sex and hypertension on cardiometabolic risk." (PMID 36017698, 2022). "Our analyses also indicated a significant interaction between RBP4 and hypertension on CVD risk (P interaction=0.04)." (PMID 36017698, 2022). "In a larger (n = 2614) cross-sectional study, RBP4 levels were positively associated with prediabetes and with several metabolic risk factors, including BMI, waist circumference, hypertension, and plasma lipids." (PMID 23936766, 2013). "Moreover, RBP4-deficient mice were protected from angiotensin II-induced hypertension and cardiac hypertrophy, thereby preserving the cardiovascular system." (PMID 39698033, 2024). "RBP4 levels in blood are associated with cardiovascular diseases such as hypertension." (PMID 35334893, 2022). "Functionally, a RBP4 loss-of-function mouse model showed lower blood pressure, enhanced (ex vivo determined) carbachol-induced vasodilatation of carotid arteries, some protection from angiotensin 2-induced hypertension, and reduced cardiac hypertrophy." (PMID 35334893, 2022). "Therefore, in this study, we sought to determine the associations among RBP4 and metabolic indices and IR in newly diagnosed, untreated hypertension patients." (PMID 24932224, 2014). "The relationship between RBP4 and hypertension might be an underlying cause in reinforcing the risk of atherogenesis." (PMID 23799122, 2013). "Taken together, our data appear to indicate that hypertension causes the different altered expression of RBP4, C3, ALBf, A1MG and A1AT in the rat serum and that the altered levels of the two latter proteins were apparently normalized when the rats were treated with captopril." (PMID 22416803, 2012). "However, hypertension state modified the association of retinol and RBP4 with cardiometabolic risk." (PMID 36017698, 2022). "Moreover, a mendelian randomization study investigating the functions of RBP-4 variants confirmed that plasma RBP-4 level was significantly associated with several metabolic parameters such as hypertriglyceridemia, abdominal obesity, hypertension, and low HDL-cholesterol." (PMID 32516964, 2020). "Supporting this, RBP4 systemic levels were described to correlate with the increased prevalence of hypertension." (PMID 38275649, 2024). "We also observed that CA patients with hypertension exhibited higher synovial RBP4 levels than normotensive patients." (PMID 38275649, 2024). "This study found that in addition to T2DM; RBP4, age, hypertension and LDL-Csignificantly affected coronary artery elasticity, which is generally consistentwith the results of previous studies." (PMID 39077416, 2023). "High urinary level of RBP-4 was an independent predictor of progressive CKD during a 24-month follow-up in severe non-alcoholic fatty liver disease(NAFLD) patients with hypertension." (PMID 36836700, 2023). "Median waist circumference and prevalence of hypertension were higher with higher retinol and higher RBP4 plasma concentrations." (PMID 36017698, 2022). "The best predictive model for females was composed of RBP4, SCr, hypertension, log insulin, and log hs-CRP (AUC: 0.824, 95% CI: 0.796–0.852, Youden’s index: 0.510, P<0.001)." (PMID 35846279, 2022). "In recent years RBP4 have achieved significant efficacy coronary heart disease, hypertension, heart failure." (PMID 35309061, 2022). "It was found that blood RBP4 levels were significantly elevated in patients with untreated essential hypertension and significantly correlated with left ventricular diastolic function." (PMID 35309061, 2022).
Hypertension (continued). "In the RBP4 tertile groups, significant differences in the occurrence of hypertension and chronic kidney disease (CKD), serum triglyceride levels, GGT activity, FLI, and eGFR values were found in both men and women." (PMID 29524177, 2018). "In our results, we found that RBP4 levels were higher in hypertension patients than in normotensive, normal-weight patients." (PMID 24932224, 2014). "This study addressed the relationship between RBP4 and IR in newly diagnosed essential hypertension." (PMID 24932224, 2014). "Interaction analyses indicated a significant interaction between RBP4 concentrations and hypertension state regarding CVD risk (P=0.035), but not for FLI or eGFR." (PMID 36017698, 2022). "Decreasing eGFR wasassociated with higher levels of RBP4 in hypertension." (PMID 39076230, 2022). "Therefore, it is worth exploring the clinical significance of RBP4 in newly diagnosed, untreated hypertension patients." (PMID 24932224, 2014). "However, in women, we found a statistically significant u-shaped association of RBP4 with T2D risk, independent of hypertension, liver, and renal function." (PMID 36017698, 2022). "RBP4 levels are closely correlated to hypertension in diabetic patients and may be engaged in regulating left ventricular diastolic function in individuals with essential hypertension." (PMID 35082965, 2022). "Retinol binding protein 4 (RBP4), forming a 1:1:1 m complex with retinol and thyroxine carrier protein in the blood, an appropriate surrogate marker for serum vitamin A level, was also in line with the increased risk of hypertriglyceridemia, high blood pressure." (PMID 35276969, 2022). "Interestingly, lowering RBP4 might reduce blood pressure through enhanced eNOS-mediated vasodilatation and may be a novel therapeutic approach for hypertension." (PMID 30038059, 2018). "The statistical significance of the interaction between RBP4 and hypertension status on CVD was not robust against multiple testing correction and replication in an independent study is indicated to inform on the generalizability of this finding." (PMID 36017698, 2022). "In women, we found a u-shaped relationship (P nonlinearity=0.01) between RBP4 and T2D (P effect=0.02) that was robust against further adjustments and in subgroups according to hypertension state, liver fat content, and renal function." (PMID 36017698, 2022). "Serum RBP4, anthropometric and metabolic parameters were determined in 267 newly diagnosed essential hypertensive patients not taking antihypertensive medications." (PMID 24932224, 2014). "Interestingly, this significant increase in RBP4 levels in CA patients with hypertension was observed in gout patients but not in pseudogout patients, which might be explained by the fact that gout is associated with more metabolic alterations than pseudogout." (PMID 38275649, 2024).
chronic kidney disease (32 papers, 2008 to 2026). Impairment of the renal function secondary to chronic kidney damage persisting for three or more months. "Inverse relations between eGFR and serum RBP-4 were found in Chronic Kidney Disease: Determinants of Progression and Cardiovascular Risk (PROGREDIR)study." (PMID 36836700, 2023). "In patients with chronic kidney disease, almost a two-fold abundance of RBP4 was associated with lower estimated glomerular filtration rate (eGFR) in HDL particles." (PMID 34575030, 2021). "However, RBP4 was significantly increased in HIV-infected patients with proteinuric chronic kidney disease, in those with overt associated lipodystrophy syndrome, and in those following treatment with highly active antiretroviral therapy." (PMID 33135589, 2020). "RBP4, a hepatically synthesized protein, plays a central role in retinol transport and is influenced by multiple pathophysiological conditions common in end-stage renal disease." (PMID 40881125, 2025). "Human RBP4 was found to be shortened by one or both leucine amino acid residues at the C-terminus in patients suffering from chronic renal failure." (PMID 35334893, 2022). "In patients with chronic kidney disease (CKD), higher serum RBP4 levels were associated with a higher rate of cardiovascular events and higher mortality, which suggests that RBP4 levels may indicate an increased risk of cardiovascular risk within this group." (PMID 32718041, 2020). "This was done to minimize confounding with respect to circulating RBP4 due to chronic kidney disease in view of the inverse relationship of RBP4 with glomerular filtration rate." (PMID 31717719, 2019). "Multivariate stepwise ordered logistic regression analysis of factors influencing RBP4 levels revealed that chronic kidney disease had the strongest influence both in crude and sex-adjusted analyses." (PMID 29524177, 2018). "KNG1and RBP4 genes were two of the top kidney up-regulated ones in an end stage renal disease (ESRD) mouse model." (PMID 26792617, 2016). "The kidneys play an important role in the metabolism of vitamin A and its transport proteins and it is well documented that a reduced kidney function due to acute or chronic renal failure is associated with increased serum concentrations of ROH, RBP4 and TTR." (PMID 22151790, 2011). "It was reported that RBP4 isoforms and levels were highly increased in the plasma of patients with chronic kidney disease, and retinol-binding protein was also identified as a biomarker of acute kidney injury." (PMID 21385403, 2011). "The kidney, the main site of RBP4 catabolism, contributes to an elevation of RBP4 levels during chronic kidney disease (CKD) whereas during chronic liver disease (CLD) RBP4 levels decrease." (PMID 18752671, 2008). "Furthermore, it appears that in ageing, the rise in RBP4 is related to the development of atherogenesis, chronic kidney disease, and osteoarthritis." (PMID 41751363, 2026). "However, in a comparison of RBP4 levels between participants with chronic kidney disease (CKD), chronic liver disease (CLD), and controls, it was shown that compared with controls, RBP4 levels were highly increased in CKD but equivalent in CLD." (PMID 37367914, 2023). "Therefore, the accumulation of retinol and RBP4 in the serum during chronic renal failure induces GPR68 expression in monocytes." (PMID 33986294, 2021). "While some post-translationally processed forms of human RBP4 have been implicated in in chronic renal failure, deimination has not been assessed." (PMID 31936359, 2020). "Furthermore, increased levels of circulating RBP4 have been described in patients with chronic renal failure and attributed to reduced glomerular filtration." (PMID 19589139, 2009). "The prognostic power of RBP4 has been supported in other populations at high cardiovascular risk like those with chronic heart failure (CHF) and chronic kidney disease (CKD)." (PMID 34758835, 2021).